TNF (tumor necrosis factor)
Diseases named in the same sentence as TNF in open-access papers (continued):
Sharing a sentence is not in itself a finding about the gene and the disease.
COVID-19 (continued). "The DPP4 inhibitor also improves bronchoalveolar lavage IL-6 and TNF-α levels in LPS-induced mice and attenuates lung injury, meaning direct stimulation of anti-inflammatory activity in the lungs may help ameliorate lung damage from COVID-19." (PMID 36341356, 2022). "Accordingly, considering the COVID-19 pandemic, modifying a substantial nigra-related co-expression network by inhibiting TNF-α signaling via the NF-κB pathway, as the most significant upregulated pathway during PD, could also reduce COVID-19 symptoms in PD patients." (PMID 36249814, 2022). "Our study showed that survivors of COVID-19 had reduced brachial artery FMD compared with healthy control and risk factor-matched control, which is independent of severity of the illness, but inversely correlated with serum concentration of TNF-α after a median of 327 days from diagnosis." (PMID 35237624, 2022). "The authors suggested that such significant changes in the lymphoid tissue could result from the overproduction of TNFα by the cells that were part of the follicle or surrounding it or from a generally high level of this cytokine circulating in patients with acute COVID-19." (PMID 35632823, 2022). "Therefore, can some TNF-α inhibitors (adalimumab, infliximab and golimumab) and IL-17 inhibitors (secukinumab and ixekizumab) which can be effectively used in the treatment of RA, AS and other diseases also treat COVID-19 and produce new indications?" (PMID 35935817, 2022). "Hence, TNFα is assumed to be a promising drug target against cytokine storm in COVID-19 patients." (PMID 36574379, 2022). "From the top 20 pathways, the TNF signaling pathway, PI3K-Akt signalling pathway, and the T cell receptor signaling pathway might be the main pathways associated with these compounds in treating COVID-19." (PMID 36506534, 2022). "For example, the TNF signaling pathway was enriched in Decidual transcripts, cytokine–cytokine receptor interaction was enriched in maternal Macrophage-2, coronavirus disease (COVID-19) was enriched in fetal Stromal-1, and degenerative diseases were associated with maternal T cells." (PMID 35042863, 2022). "However, with the results we obtained regarding TNF- α, we suggest that off-concentrations of it might be used to depict the unbalanced immune response of COVID-19 patients." (PMID 36530391, 2022). "In addition, cell concentration revealed that these specific subsets were mainly involved in some inflammatory pathways, such as coronavirus of COVID-19, IL-17 signaling pathway, chemokine signaling pathway, TNF signaling pathway, and viral protein interaction between cytokine and its receptor." (PMID 35911765, 2022). "Interestingly, IDO1 inhibitors suppress the COVID-19-induced pro-inflammatory cytokine release, including TNF-α, IL-6, IL-1α and IL-1β in isolated PBMCs derived from COVID-19-infected rhesus macaques and lower mortality among critically ill patients with COVID-19." (PMID 36589459, 2022). "Following preincubation for 1 h of PBMC with the extract, a significant inhibition of IL-1β, TNF, and IL-6 was observed at a concentration of 5 or 10 μg/mL, with a similar potency when compared to 1 μM dexamethasone, the current reference treatment for COVID-19." (PMID 35455990, 2022). "Consequently, after COVID-19 antigen exposure, this metabolic inflammation may impair macrophage activation, exaggerate pro- inflammatory cytokines/chemokines like TNF-a, IFN-g and alter innate/adaptive immunity." (PMID 36105809, 2022). "We found that plasma exosomes from COVID-19 patients significantly induced the production of the same set of cytokines and chemokines that contribute to the severity of COVID-1949–53, including IL-6, IL-8, TNF-α, IFNγ, CCL1, and GDF-15, in PBMCs compared with those from non-COVID donors." (PMID 36526691, 2022).
COVID-19 (continued). "Furthermore, recent studies are showing that NK cells from COVID-19 severe patients had a reduced cell-cell interaction and degranulation possibly caused by an early expression of TGFB and a dysregulated IFN-α and TNF response." (PMID 35893398, 2022). "It is still not clear whether a single cytokine blockade (such as TNF-α inhibitors) could be effective in CRS associated with COVID-19." (PMID 35464491, 2022). "Patients with severe COVID-19 exhibit systemic hyper-inflammation characterized by a cytokine storm, including an excessive release of pro-inflammatory mediators, such as interleukin (IL)-1, IL-6, IL-8 and tumor necrosis factor-alpha (TNF-α), which in turn is responsible for ARDS." (PMID 36671418, 2022). "Therefore, we have then evaluated the levels of TNFα and IL-1β in saliva of COVID-19 patients." (PMID 36136963, 2022). "Mainly, TNF, IL-6, and IL-8 were lower in COVID-19 compared to patients with septic shock/ARDS, and due to IL-6 and IL-8 was near eightfold lower, it was suggested that cytokine storm does not characterize COVID-19, and it could be one of the reasons for the immunosuppressive therapies fail." (PMID 35631442, 2022). "Thus, three targets (RELA, TNF, and VEGFA) linked to the MAPK signaling pathway might be promising targets for use against COVID-19." (PMID 35678652, 2022). "Regarding the association between COVID-19 severity and risk factors, a logistic regression analysis stepwise method revealed that older age (OR = 1.07), high BMI (OR = 1.18), and the steroid use (OR = 1.74) were risk factors for COVID-19, but anti-TNFα antibodies was not." (PMID 35089397, 2022). "It was reported that severe COVID-19 cases had high levels of pro-inflammatory cytokines in the germinal center, which could have generated a high-quality antibody response to establish long-term immunity, including TNF-α." (PMID 35350754, 2022). "Moreover, a new trial recently launched will investigate whether adalimumab, an anti-TNF drug, is effective for treating COVID-19 patients in the community." (PMID 35335008, 2022). "Similarly, there is evidence for an important role of TNF-α in COVID-19." (PMID 36297092, 2022). "CoV-2 infection of IECs stimulated robust IFN-γ, Granzyme B, TNF-α production in MAIT cells." (PMID 36825215, 2022). "These miRNAs target several pro-inflammatory cytokine and chemokine genes (e.g., TNF, CCL2, CXCL9, CXCL10, IL10, VEGFA) as well as cytokine and chemokine receptors and transduction factors (IL1R1, IL2RA, IFNAR2), reported as upregulated and associated with mortality in COVID-19 patients." (PMID 36032130, 2022). "These commonalities may explain why AID patients treated with biologicals such as IL-1 inhibition, TNFα inhibition, and IL-6 inhibition are not at greater risk of severe COVID-19." (PMID 36034552, 2022). "Therefore, targeting TNF-α is also a potential pharmacological treatment for COVID-19." (PMID 36146616, 2022). "Some Chinese herbs such as quercetin and baicalin can bind to CCL2 receptor and thus act on immune response signaling pathway, tumor necrosis factor signaling pathway, and influenza A signaling pathway, which may play a dual role in anti-COVID-19 and GBM process." (PMID 35726234, 2022). "Cytokine dysregulation (particularly transforming growth factor-β (TGF-β), Tumor Necrosis Factor (TNF)-α, Interleukin (IL)-1β, Interferon (IFN)-γ, IL-6, and IL-10) are known to be associated with psychiatric disorders, and have been shown to be elevated in patients with COVID-19." (PMID 35053059, 2022). "Thus, PIBD patients on anti-TNFα should be more careful about COVID-19 even after the initial vaccine series, and they may receive the third vaccine as soon as possible compared to patients receiving other IBD treatments." (PMID 36298483, 2022).
COVID-19 (continued). "Severe COVID-19 patients also mostly exerted viral infection-induced hyperinflammatory state, mainly characterized by sustained increases in TNF-α, IL-6, and IL-1 levels, and disrupted monocyte and dendritic cell phenotypes, which could ultimately contribute to poor prognosis and mortality." (PMID 34593760, 2021). "Indeed, both scATAC-seq and scRNA-seq KEGG analyses revealed the TNF signaling pathway to be involved in COVID-19; the scATAC-seq data showing lower TBX21 locus accessibility were consistent with the scRNA-seq data, showing decrease in Th1 cells of SCPs compared to the MCPs and HCs." (PMID 33717140, 2021). "The XBJ injection may inhibit the lipopolysaccharide-mediated inflammatory response, modulate NOS activity, and regulate the TNF signaling pathway by affecting the function of the AKT1, thereby ultimately suppressing the excessive inflammatory response associated with COVID-19." (PMID 34077310, 2021). "A cross-sectional study found a correlation between higher inflammatory markers in the serum of patients with more severe COVID-19, including cytokines such as IL-2R, IL-6, and TNF-a, suggesting that the inflammation level may predict disease severity in COVID-19." (PMID 34367693, 2021). "Finally, we employed a structure-based molecular docking method to demonstrate that the andrographolide could bind with TNF and NFkB1, potentially blocking the TNF-mediated NFkB1 pathway underpinning cytokine storm in severe patients with COVID-19." (PMID 34248936, 2021). "In addition, TNF-α can promote aged T cell apoptosis, which may contribute to lymphopenia in the severe course of COVID-19 in older patients." (PMID 34858428, 2021). "Thus, TNF-α accelerates the activation of immune cells, which can result in uncontrolled inflammatory response and tissue damage under certain circumstances, like in the case of COVID-19 cytokine storm." (PMID 33445810, 2021). "Our study supports a key role for IFN-γ together with TNF-α in driving an abundant inflammatory macrophage phenotype in severe COVID-19-affected lungs, as well as inflamed RA synovium, CD ileum, and UC colon, which may be targeted by existing immunomodulatory therapies." (PMID 33879239, 2021). "The evidence of massively high levels of a subset of cytokines—such as IL-6 and TNF-α—in critically ill patients has led to the hypothesis that, in the setting of the COVID-19-related cytokine storm, they could have a major role in enhancing the endothelial damage." (PMID 34769454, 2021). "As it was shown for COVID-19 infection that levels of IL-6, along with IL-8 and TNF-α, were powerful predictors of severity and survival at the time of hospitalization, using IL-6 inhibitors could be a promising therapy against sever COVID-19." (PMID 33441142, 2021). "In this study, the levels of TNF-α, IL-1α, IL-4, IL-6, IL-8, and IL-10, were measured through ELISA in sera from healthy volunteers as a control group, patients with moderate COVID-19, patients with severe COVID-19, and patients who had recovered from COVID-19." (PMID 33914789, 2021). "Whereas serum of non-COVID-19 patients and anti-spike IgG-negative COVID-19 patients showed no up-regulation of pro-inflammatory cytokines compared to individual poly(I:C) stimulation, IL-1β, IL-6, IL-8, and TNF production was amplified by serum of COVID-19 patients with anti-spike IgG (P <0.0001)." (PMID 33979301, 2021). "Moreover, R. crenulata might play an anti-inflammatory and immunoregulatory role in the cytokine storm of COVID-19 by acting on IL-1β, IL-6 and TNF-α." (PMID 34313585, 2021). "In addition, neutrophils, which are increased in the blood and tissues of COVID-19 patients, may contribute to the endothelial damage and thus the release of tumor necrosis factor (TNF)-alpha, interleukin (IL)-1, and IL-8." (PMID 34572581, 2021).
COVID-19 (continued). "Therefore, an induction of T-cell apoptosis could, similar to MERS-CoV infections, be a mechanism by which SARS-CoV-2 causes a dysregulated immune response, mediated by the elevated plasma levels of TNF-α often seen in severe COVID-19 cases." (PMID 34452323, 2021). "Otherwise, in the acute phase of COVID-19, a storm of plasma cytokines and chemokines has been described, with higher markers of inflammation (e.g. C-reactive protein, ferritin, IL-2 IL-4, IL-6, IL-8, IL-10, TNF-α, and INF-γ) in patients with more severe presentations." (PMID 33890193, 2021). "In particular, the class of anti-TNFα antibodies, mostly used for the treatment of inflammatory rheumatic diseases, could be able to challenge COVID-19 by two main actions: the classical TNFα inhibition and a down-regulation of ACE2 expression resulting in decreased binding sites for SARS-CoV-2." (PMID 33544720, 2021). "The first-line signals including interferon (IFN) signals and NOD-like receptor family pyrin domain containing 3 (NLRP3) inflammasome may be the most dominant, explained by the uncoordinated IFN responses that amplify TNF/IL-1β-centered hyperinflammatory signatures in severe COVID-19 patients." (PMID 34650550, 2021). "Furthermore, NF-κB, IL-6, and TNF are considered promising therapeutic targets in COVID-19." (PMID 34580601, 2021). "Moreover, antidepressant use has been associated with a reduced risk of intubation or death in hospitalized patients with COVID-19 because the inhibition of ASM decreases pro-inflammatory mediators such as IL-2, IL-6, IL-7, IL-10, TNF-α, C-reactive protein (CRP), and D-dimer." (PMID 34579284, 2021). "Furthermore, in COVID-19 therapy, ruxolitinib (Henan DaKen Chemical Co., Ltd., Zhengzhou, China), a JAK-STAT antagonist that inhibits IFN-gamma, is being used, and TNF-suppressing antibodies such as adalimumab and golimumab were also employed to manage COVID-19 cases with severe immune response." (PMID 33946736, 2021). "However, currently there is insufficient evidence to ascertain whether COVID-19 vaccine effectiveness is diminished also by higher doses of conventional immunosuppressants or other biological agents such as anti-TNFα." (PMID 33936084, 2021). "Moreover, symptomatic children with COVID-19 were found to have higher viral load, lower total lymphocyte count, lower lymphocyte subsets, and elevated interleukin 6 (IL-6), IL-10, tumor necrosis factor-alpha (TNF-α), and interferon-gamma (IFN-γ) levels compared with asymptomatic patients." (PMID 34975908, 2021). "Importantly, IL-6, TNF-α have been reported to predict the severity of COVID-19 patients." (PMID 33763078, 2021). "Moreover, IL-17 positively correlated with TNF-α levels in the critically ill COVID-19 patients." (PMID 34575667, 2021). "Notably, in the recent COVID-19 outbreak, a cytokine profile resembling sHLH was found to be associated with COVID-19 disease severity, characterized by increased cytokines such as IFNγ, MCP-1, MIP1-α, and TNFα." (PMID 33823154, 2021). "TNF was barely detectable in COVID-19 serum samples and highest in individuals with moderate disease, suggesting that another cytokine, for example IL-6, or stimulus may be responsible for NF-κB activation in asymptomatic individuals with COVID-19." (PMID 33879890, 2021). "In addition, in the same experimental setting we found a remarkable production of inflammatory cytokines such as IL-6, TNF-α and IL-1β, which are well-recognized players of the cytokine storm occurring in COVID-19 patients, while IL-12p70 level was unchanged in SARS-CoV-2-stimulated PBMC." (PMID 34473805, 2021). "In addition to increased levels of sICAM-1, we found that TNFα was also elevated after COVID-19." (PMID 34838058, 2021).
COVID-19 (continued). "Cumulative reports correlate the severity of COVID-19 with the excessively-heightened level of pro-inflammatory mediators including interleukin 1 (IL-1), interleukin 6 (IL-6), tumor necrosis factor-alpha (TNF-α), alongside multiple agents, lists of which reported elsewhere." (PMID 33888147, 2021). "However, normal levels of TNF-α have been reported in severe COVID-19 patients." (PMID 34276659, 2021). "In addition, increased levels of proinflammatory cytokines (Interleukin-1, Interleukin-6, and TNF) were found in COVID-19 patients, which may explain the endothelial dysfunction to some degree." (PMID 34945800, 2021). "Therefore, anti-TNF-α treatment for severe COVID-19 patients could be a better choice to improve the mortality rate." (PMID 34725309, 2021). "Finally, increased IL-17 production by Th17 cells in COVID-19 patients has broad pro-inflammatory effects through the upregulation of pro-inflammatory cytokines like G-CSF, IL-1β, IL-6, TNFα, as well as chemokines like MIP2A, IL-8, IP10, MIP3A, and matrix metalloproteinases." (PMID 34512643, 2021). "Most COVID-19 patients exhibit increased circulating levels of IL-6, IL-1b, and TNF, as well as IL-2, IL-8, reflecting the disease severity, which results in massive systemic immunosuppression and in lymphopenia and neutrophilia, two key hematological features of COVID-19." (PMID 33815868, 2021). "These alterations in COVID-19 may be linked to the STAT1/IRF1 signaling pathway, which is activated by the combined action of TNF- and IFN- in macrophages, resulting in the activation of iNOS and various forms of programmed cell death (pyroptosis, apoptosis, and necroptosis)." (PMID 34299201, 2021). "However, the molecular interactions behind the dysregulation of the TNF and IL-17 signaling pathways seen in severe cases of COVID-19 are still unknown." (PMID 33802569, 2021). "Similarly to SARS, inflammation plays an important role in the pathophysiology of COVID-19, and patients with severe disease may have high serum concentrations of inflammatory markers such as IL-6, TNF, C-reactive protein (CRP), and D-dimer." (PMID 34960790, 2021). "For example, TNF-α and interleukin (IL)-6 impair mitochondrial oxidative phosphorylation and coupled ATP production and trigger the production of mitochondrial ROS in the cell, leading to mitochondrial dysfunction, which has been found expressed in patients with COVID-19." (PMID 34204362, 2021). "However, it is worth noting that most of the currently tested immunomodulatory agents (especially anti-IL-6, anti-IL-1β, and anti-TNFα) have been put forward despite gaps in our understanding of the immune response behind COVID-19 ARDS, especially within the pulmonary compartment." (PMID 33138839, 2020). "We have previously shown the neuroprotective potential of naringenin through modulation of inflammatory mediators (NF-κB, TNF-α, IL-1β, etc) and microglia activation in the CNS, thereby it could mitigate the neuronal signs of COVID-19 mediated by the inflammatory mediators." (PMID 33708124, 2020). "Moreover, the clinical trial of anti-TNFα in treating COVID-19 (ChiCTR2000030089) is ongoing." (PMID 33511147, 2020). "In COVID-19 patients, innate immune cells, including dendritic cells and macrophages, were activated upon sensing of coronaviruses via toll-like receptors, which induced the expression of pro-inflammatory cytokines (e.g., IL-1, IL-6, TNF-a) through engagement with NF-κB signaling." (PMID 33195318, 2020). "Besides, another study reported that 7 COVID-19 patients treated with MSCs showed significant improvement in symptoms within 2 days of treatment, while increase in lymphocytes, decrease in cytokine-secreting immune cells and TNFα was observed after 3–5 days." (PMID 32784499, 2020).